DYNLL2 (dynein light chain LC8-type 2)
Description:
Acts as one of several non-catalytic accessory components of the cytoplasmic dynein 1 complex that are thought to be involved in linking dynein to cargos and to adapter proteins that regulate dynein function. Cytoplasmic dynein 1 acts as a motor for the intracellular retrograde motility of vesicles and organelles along microtubules. May play a role in changing or maintaining the spatial distribution of cytoskeletal structures (By similarity).
Synonyms: DLC2; MGC17810; DNCL1B; RSPH22
Tractability: Antibody: its Gene Ontology location is reachable by antibodies, with high confidence. PROTAC: ubiquitination databases record sites on it; its protein half-life has been measured.
Gene: Protein-coding gene on chromosome 17 (58,082,863 to 58,095,542, forward strand). Ensembl gene ENSG00000264364.
Subcellular location: Cytoplasm, cytoskeleton
Subcellular location (Human Protein Atlas): Cytosol; Mid piece; Nucleoplasm; Principal piece
Pathways (Reactome):
Cell Cycle: Amplification of signal from unattached kinetochores via a MAD2 inhibitory signal; EML4 and NUDC in mitotic spindle formation; Mitotic Prometaphase; Resolution of Sister Chromatid Cohesion; Separation of Sister Chromatids
Autophagy: Aggrephagy; Macroautophagy
Vesicle-mediated transport: COPI-independent Golgi-to-ER retrograde traffic; COPI-mediated anterograde transport
Cellular responses to stimuli: HSP90 chaperone cycle for steroid hormone receptors (SHR) in the presence of ligand
Disease: HCMV Early Events
Immune System: MHC class II antigen presentation
Organelle biogenesis and maintenance: Intraflagellar transport
Programmed Cell Death: Activation of BMF and translocation to mitochondria
Signal Transduction: RHO GTPases Activate Formins
Gene Ontology:
Molecular function: protein binding; dynein intermediate chain binding; identical protein binding; protein-containing complex binding; scaffold protein binding
Biological process: cilium movement; flagellated sperm motility; intraciliary retrograde transport; positive regulation of intracellular transport; positive regulation of mitotic cell cycle spindle assembly checkpoint; microtubule-based process
Cellular component: 9+0 non-motile cilium; centrosome; cytoskeleton; glutamatergic synapse; membrane; nucleus; postsynapse; 9+2 motile cilium; axoneme; ciliary tip; cilium; cytoplasmic dynein complex; cytosol; dynein complex; male germ cell nucleus; myosin V complex; plasma membrane; radial spoke; sperm flagellum; microtubule associated complex; microtubule cytoskeleton; postsynaptic density
Genetic constraint (gnomAD): Loss-of-function variants: 1 observed, 10.27 expected, observed/expected ratio (o/e) 0.0974, 90% interval 0.034 to 0.46. The upper end of that interval is the gene's LOEUF score, 0.46, which puts it in group 2 of 6, group 1 being the genes least tolerant of losing a copy. Missense variants: 37 observed, 121.78 expected, observed/expected ratio (o/e) 0.3, 90% interval 0.23 to 0.4. Synonymous variants: 35 observed, 42.08 expected, observed/expected ratio (o/e) 0.83, 90% interval 0.63 to 1.1.
Homologues: Orthologues: chimpanzee DYNLL2 (100% identical), dog DYNLL2 (100% identical), guinea pig DYNLL2 (100% identical), macaque DYNLL2 (100% identical), mouse Dynll2 (100% identical), pig DYNLL2 (100% identical), rabbit DYNLL2 (100% identical), rat Dynll2 (100% identical), tropical clawed frog vti1b (100% identical), zebrafish dynll2a (99% identical), zebrafish dynll2b (99% identical), Drosophila melanogaster ctp (97% identical), and 2 more. Paralogues in human: DYNLL1 (93% identical).
Diseases named in the same sentence as DYNLL2 in open-access papers:
DYNLL2 is named in the same sentence as 21 diseases in open-access papers, as found by Europe PMC text mining. Sharing a sentence is not in itself a finding about the gene and the disease. The quoted sentences say what the papers report.
hepatocellular carcinoma (3 papers, 2020 to 2023). A malignant tumor that arises from hepatocytes. "Moreover, previous studies have reported that DYNLL2 is associated with drug resistance to sorafenib in patients with hepatocellular carcinoma." (PMID 33584797, 2020). "Previous studies have demonstrated that DYNLL2 is a key gene in hepatocellular carcinoma and plays an integral role in cancer development." (PMID 33968741, 2021).
Anxiety (2 papers, 2023 to 2025). Intense feelings of nervousness, tension, or panic often arise in response to interpersonal stresses. "We reproduced and expanded our earlier findings in an animal model of GABBR1, CCKBR, and DYNLL2 as top genes involved in anxiety." (PMID 36878964, 2023). "Notably, although it was not directly linked to the HPA axis, DYNLL2 was the only one of the top biomarkers that was modulated by benzodiazepines, though in the opposite direction to what is normally observed in high-anxiety conditions." (PMID 40508224, 2025). "Only one of the top biomarkers, DYNLL2, has evidence for being modulated by benzodiazepines in the opposite direction to that in high anxiety; the others do not, which is interesting and clinically useful, as it brings to the fore other, non-addictive, choices." (PMID 36878964, 2023).
osteosarcoma (2 papers, 2021 to 2023). A usually aggressive malignant bone-forming mesenchymal neoplasm, predominantly affecting adolescents and young adults. "All evidence from our study demonstrates that TRIM68, PIKFYVE, and DYNLL2 are high-risk genes involved in the development of osteosarcoma and can be used as biomarkers for predicting the prognosis of osteosarcoma." (PMID 33968741, 2021). "TRIM68, PIKFYVE, and DYNLL2 are high-risk genes involved in the development of osteosarcoma and can be used as possible biomarkers for predicting the prognosis of osteosarcoma." (PMID 33968741, 2021). "The TRIM68, PIKFYVE, and DYNLL2 genes can be used as biomarkers for predicting the prognosis of osteosarcoma." (PMID 33968741, 2021). "The expressions of TRIM68, PIKFYVE, and DYNLL2 were higher in the osteosarcoma cells compared to the control cells." (PMID 33968741, 2021). "DYNLL2 has been identified as a novel prognostic biomarker for ischemic stroke and osteosarcoma, but its role in azoospermia and COVID-19 has not been revealed." (PMID 37283758, 2023).
Azoospermia (1 paper, 2023). Absence of any measurable level of sperm,whereby spermatozoa cannot be observed even after centrifugation of the semen pellet. "Our study demonstrated a positive correlation between DYNLL2 and T helper cells, as well as an association with the IL-17 signaling pathway in azoospermia and COVID-19." (PMID 37283758, 2023). "In this study, we identified four genes, GLO1, GPR135, DYNLL2, and EPB41L3 that were strongly associated with azoospermia and COVID-19." (PMID 37283758, 2023). "The expression levels of GPR135 in azoospermia tissues positively correlated with the levels of “DYNLL2” and “EPB41L3” and negatively correlated with GLO1 expression." (PMID 37283758, 2023).
colorectal tumors (1 paper, 2022). "There is a negative correlation between DYNLL2 expression and macrophage M0, the most abundant cells in stage N1 colorectal tumors." (PMID 36761693, 2022).
pancreatic adenocarcinoma (1 paper, 2023). "Compared with normal tissues, the expression levels of MET, DYNLL2, CDK1, TNFSF10, PIP5K1C, MSLN, and GKN1 were significantly increased in pancreatic adenocarcinoma cells (p < 0.05)." (PMID 37370756, 2023). "We identified seven prognostic genes (MET, DYNLL2, CDK1, TNFSF10, PIP5K1C, MSLN, GKN1) and validated that their related proteins, such as EGFR and MMP2, have a significant impact on the prognosis of pancreatic adenocarcinoma." (PMID 37370756, 2023). "No study has confirmed that DYNLL2 and PIP5K1C are prognostic protective gene for pancreatic adenocarcinoma, and this study is the first to do so." (PMID 37370756, 2023).
Stroke (1 paper, 2021). Sudden impairment of blood flow to a part of the brain due to occlusion or rupture of an artery to the brain. "Calcium signaling pathway-related genes (AC079305.10, BCL10, BCL2A1, BRE-AS1, DYNLL2, EREG, and PTGS2) are related to apoptosis after stroke, whereas posttranscriptional regulation of BCL2A1 may be possibly associated with IS." (PMID 34987704, 2021).
tumor (1 paper, 2022). "Dynein light chain LC8-type 2(DYNLL2) is involved in cytoskeletal motor activity and protein binding, which plays an important role in the tumor microenvironment." (PMID 36761693, 2022).
DYNLL2 also shares sentences with these, for which no sentence is quoted: Bardet-Biedl syndrome (1 paper); cancer (1); ciliopathies (1); congenital hydrocephalus (1); COVID-19 (1); generalized anxiety disorder (1); genetic disease (1); infection (1); ischemic stroke (1); joint effusion (1); neurodegenerative disease (1); oculocerebrorenal syndrome (1); short-rib thoracic dysplasia (1).